IL1B (interleukin 1 beta)
Diseases named in the same sentence as IL1B in open-access papers (continued):
Sharing a sentence is not in itself a finding about the gene and the disease.
Obesity (continued). "For instance, promoted oxidative stress and suppressed immune system are linked with increases in inflammatory factors and adipokines (TNF, leptin, IL-1β, and IL-6) in obesity." (PMID 35628513, 2022). "Considering the critical crosstalk between obesity, NASH, and HCC, this review will present the connections of IL-1β and IL-18 from obesity-associated NASH with HCC and will discuss approaches to using these cytokines as therapeutic targets against HCC." (PMID 36289606, 2022). "It has been reported that the fat factor RETN can activate obesity-related inflammatory responses through the combined action of the pro-inflammatory cytokine IL-1β." (PMID 36401283, 2022). "SBH and Sim inhibited the inflammation accompanied by obesity via decreasing inflammatory cytokine interleukin (IL)-1β, tumor necrosis factor α (TNFα), and monocyte chemoattractant protein 1 (MCP1)." (PMID 35889886, 2022). "The observation that monocytes and MDM from patients with obesity show an increased [Ca2+]ex-induced IL-1β response already before they enter the tissue indicates, that those alteration occur during myelopoiesis in the bone marrow." (PMID 35931812, 2022). "Studies have shown that IL-1β is related to many chronic diseases such as rheumatoid arthritis, obesity, and type II diabetes." (PMID 34683827, 2021). "Obesity is a chronic systemic inflammation, which can induce macrophages to produce IL-1β and increase the circulating IL-1β concentration." (PMID 34683827, 2021). "Obesity is associated with activation of the NLRC4 inflammasome, enrichment of TAMs, elevated IL-1β, and increased angiogenesis." (PMID 33815289, 2021). "In this study, we found that HIF-1α mediates MCP1, TNFα, and IFNγ production and that HIF-1α-mediated impairment of liver and EWAT increases IL-1β production, which induced M1 polarization in mice contributing to obesity-induced NAFLD." (PMID 34360607, 2021). "Noteworthy, failure in ovarian leptin signaling in late obesity was associated with the repression in NLRP3 activity, but with maintenance of inflammation and levels of IL-1β." (PMID 34805147, 2021). "In this study, we developed a novel weight loss strategy through yeast microcapsule mediated oral delivery of IL-1β shRNA to regulate the expression of obesity-related gene and inflammatory response." (PMID 34683827, 2021). "Accumulating evidence confirms that IL-1β and MCP-1 are critically involved in obesity-associated inflammation in the rodent models." (PMID 33859296, 2021). "β-cells can also produce IL1β, probably initiating the inflammatory process (see in Section 3.4.2); however, macrophages are seemingly the major source of islet IL1β production in obesity." (PMID 33801681, 2021). "During obesity, macrophages accumulate in the adipose tissue and shift to a pro-inflammatory state, exemplified by increased expression of IL-1β, TNF and IL-6." (PMID 34201844, 2021). "In monocytes, saturated fatty acids activate caspase-4/5 to induce the production and release of IL-1β and IL-18, eventually leading to obesity-related inflammation." (PMID 34737754, 2021). "Consistent, with obesity-induced neuroinflammation, expression of Il1b was higher in HFD treated mice as compared to normal chow fed mice." (PMID 34093866, 2021). "Reduced secretion of IL-1β in the obese chicken model used here (i.e., Ad-hens) contrasts sharply with most reports in models of mammalian obesity, T2DM, and cellular models of glucolipotoxocity." (PMID 34200930, 2021). "In two syngeneic orthotopic transplant models, a NLRC4 inflammasome/IL-1β signaling was demonstrated to provide a link between obesity and breast cancer progression." (PMID 33987528, 2021). "Leptin induces the expression of TNF-α, IL-6, and IL-1β in adipose tissue cells, contributing to insulin resistance, and is considered one of the links between obesity, insulin resistance, and atherosclerosis." (PMID 33520042, 2021).
Obesity (continued). "Obesity is associated with macrophage activation and production of pro-inflammatory cytokines including TNF-α, IL-1b, and IL-6." (PMID 34970568, 2021). "Obesity can cause disorders in the BTB structure, and the expression of IL-1β protein remarkably increased in the blood." (PMID 34248933, 2021). "Analysis of circulating cytokines revealed increased serum IL1b with dietary obesity in B6.scid mice, consistent with the persistent pro-inflammatory effects of high-fat diet reported by other groups using this model." (PMID 34330904, 2021). "In obesity, there is an expansion of fat tissue and increased release of pro-inflammatory mediators, including IL-1β, which have been proposed to impair insulin action." (PMID 34638553, 2021). "The high levels of IL-1β in response to obesity induce the expression of Angiopoietin-like 4 (ANGPTL4) from primary adipocytes in a manner dependent on NF-κB- and MAPK-activation, which is enhanced by hypoxia." (PMID 33815289, 2021). "ILC2s can indirectly regulate type 1 cytokines such as TNF-α and IL-1β, found in cases of obesity, through influencing M1 macrophage polarization." (PMID 34489979, 2021). "Children with obesity had a large scale of adipocytes, which promoted macrophage to accumulate and release of the proinflammatory cytokines, including IL-6, IL-1β, and TNF-α, which showed some degree of chronic inflammation." (PMID 34258058, 2021). "Obesity is also associated with an elevated level of pro-inflammatory cytokines and chemokines IL-6, RANTES, and IL-1β and of the hormone leptin, which maintains homeostatic control of AT mass." (PMID 34248964, 2021). "Interestingly, the same authors reported that, both in mouse models of PC and in patients, obesity promotes tumor desmoplasia and PC growth by a complex cross-talk among adipocytes, tumor-associated neutrophils (TANs) recruited by adipocyte-secreted IL1β and pancreatic stellate cells (PSCs)." (PMID 34439102, 2021). "Animal models demonstrated that obesity and excessive nutrition increased the concentrations of IL1B and other proinflammatory cytokines, which resulted in the development of insulin resistance and inordinate fetal growth." (PMID 33923632, 2021). "Increased levels of IL-1β and IL-6 were detected in patients with T2D and obesity, and they promoted the inflammatory process." (PMID 33921314, 2021). "TNF-α and IL-1β play key roles in the obesity, T2D, and metabolic disorders, disrupting the insulin and lipid signaling pathways, thereby influencing insulin sensitivity and lipid metabolism." (PMID 34712684, 2021). "Compared with the control groups, the expression of obesity related gene IL-1β and FAS was decreased in the experimental group." (PMID 34683827, 2021). "A link between obesity and inflammation has been established, and specifically the secretion of proinflammatory adipokines such as IL-1β, IL-6, TNF-α, and MCP-1 is increased." (PMID 34356649, 2021). "In a model of obesity induced with a hypercaloric diet in Sprague Dawley rats, an increase in proinflammatory markers such as IL-1β and TNF-α was also observed along with oxidative stress." (PMID 34336096, 2021). "Not surprisingly, substantial evidence supports both the higher circulatory levels and adipose expression of these proinflammatory cytokines (IL-6, TNFα and IL-1β) in obesity settings." (PMID 34831450, 2021). "Obesity is systemic inflammation, which can induce macrophages to produce IL-1β and increase the circulating IL-1β concentration." (PMID 34683827, 2021). "Ovalbumin-stimulated induction of Il1b was increased in microglia from mice with dietary obesity, relative to lean mice, but increases were comparable in cells from sham-operated mice and SAT transplant recipients." (PMID 34330904, 2021). "TNF-α, Il-1β, IL-6 and IL-8 are involved both in the pathogenesis of HS as well as in the development of glucose intolerance, obesity, hyperlipidemia, metabolic syndrome and atherosclerosis." (PMID 34830597, 2021).
Obesity (continued). "HMG20A expression was upregulated in diet-induced obesity and glucose intolerant mice, correlating with increased transcript levels of Gfap and Il1b indicative of inflammation and reactive astrogliosis." (PMID 34093866, 2021). "The mRNA levels of iNOS, MCP1, TNFα, and IL1β, which were M1 phenotypes induced by obesity, were significantly decreased in SVF from HFD-fed mice treated with hASCs." (PMID 34222665, 2021). "Circulating levels of IL-1β are higher in T2DM and macrophages are the primary source of IL-1β in obesity-induced inflammation." (PMID 33692997, 2021). "In pre-clinical renal cancer modeling, aggressive intratumoral MDSC infiltration in mice with diet-induced obesity (DIO) is facilitated by elevated local concentrations of IL-1b and CCL2, resulting in unfavorable ratios of MDSCs to CD8+ TILs." (PMID 34421889, 2021). "Obesity is a chronic low-grade inflammation, and the concentrations of resistin, leptin, and IL-1β, as well as TNF-α and IL-6, in peripheral blood of obese patients were significantly increased." (PMID 32104715, 2020). "IL-6 and IL-1β are proinflammatory cytokines, chronically elevated in the presence of obesity, that affect insulin resistance." (PMID 32218700, 2020). "Both excessive compressive mechanical force and high fat diet induced obesity caused TMJ osteoarthritis-like changes and increased expression of IL-1β, MMP-3, and leptin." (PMID 33060739, 2020). "We found that most of the analyzed cytokines (IL-1β, IL-8, IL-10, TNF-α, tPAI-1, MCP-1, and adiponectin) were associated with obesity." (PMID 32545403, 2020). "In addition to TNF-α, other humoral agents associated with obesity might also be contributing to the activation of WNT signaling like IL-1β and adiponectin, which is decreased in the obese state and is not an inflammatory cytokine that can modulate GSK3β/β-Catenin signaling pathway." (PMID 32811441, 2020). "While deletion of HIF-1α reduces local and systemic IL-1β levels, and causes an enrichment of M2 macrophages in the WAT, this is not sufficient to reverse the metabolic dysfunction associated with obesity." (PMID 32221369, 2020). "In randomized controlled trials, curcumin supplementation reduced serum IL-1β and IL-4 in adults with obesity (1 g/d for 8 wk) and reduced serum IL-6, MCP-1, and TNF-α concentrations in subjects with metabolic syndrome (1 g/d for 4 wk)." (PMID 32211803, 2020). "In obesity, the dysfunctional adipose tissue (AT) releases increased levels of proinflammatory adipokines such as TNFα, IL-6, and IL-1β and free fatty acids (FFAs), characterizing a chronic, low-grade inflammation." (PMID 32947825, 2020). "Further studies found that IL-1β promoted obesity-driven breast cancer angiogenesis and progression via the upregulation of angiopoietin-like 4 (ANGPTL4) in adipocytes." (PMID 32630445, 2020). "Saturated fatty acids and ceramide, associated with obesity and nutrient overload, can also trigger NLRP3 inflammasome to produce IL-1β that acts on the liver and impairs the activity of liver insulin, contributing to insulin resistance." (PMID 33113859, 2020). "Obesity-associated insulin resistance is associated with increased levels of pro-inflammatory cytokines, such as TNF-α, IL-1β, and IL-6." (PMID 33260769, 2020). "Using syngeneic breast cancer models in mice, we have shown that obesity leads to the NLRC4-inflammasome-mediated activation of IL-1β in infiltrating macrophages, which in turn promotes increased angiogenesis and disease progression." (PMID 32630445, 2020). "IL-1 family cytokines, including IL-1β and IL-18, mediate both obesity- and aging-induced metabolic complications." (PMID 32545355, 2020). "Increased levels of pro-inflammatory cytokines, such as TNF-α, IL-1β, IL-6, and IL-12, were observed in the intestinal tissue of mouse models with obesity, which was consistent with the present findings." (PMID 33329010, 2020).
Obesity (continued). "Factorial analysis showed that burn and obesity factors had an interactive effect on the expression of IL-1β gene on days 3 and 7, when the level of IL-1β gene in the obese group was higher than that in the overweight and normal weight groups (P < 0.05)." (PMID 33354433, 2020). "Considering that the M1 macrophages produce various types of inflammatory cytokines, such as TNF-α and IL-1β, which play an important role in the propagation of obesity-related inflammation, we thus focused on the pro-inflammatory cytokines in M1-sup." (PMID 32699606, 2020). "Human studies indicated that NLRP3 activity in adipose tissues positively correlates with obesity and its metabolic complications, and treatment with the IL-1β antibody improves glycaemia control in type 2 diabetic patients." (PMID 32545355, 2020). "Palmitic acid, an abundant SFA usually elevated in obesity and diabetes, induces IL-1β production in macrophages and dendritic cells via multiple pathways." (PMID 32545355, 2020). "And NLRC4 was recently shown to promote mammary tumor growth in a model of high fat diet-induced obesity via the production of IL-1β." (PMID 33042810, 2020). "A HFCM containing 6 g spice blend attenuated HFCM-induced postprandial IL-1β secretion in men with overweight/obesity." (PMID 32211803, 2020). "Obesity activates inflammasome NLRP3 and increases IL-1β through activation of caspase 1 and causes insulin resistance and reduction in fat oxidation." (PMID 33113859, 2020). "Of 38 plasma proteins analyzed, six (CCL3, IL-1β, IL-1RA, IL-10, IL-17, and TNFα) were upregulated specifically in ccRCC subjects with obesity versus tumor-free controls with obesity." (PMID 32469992, 2020). "The serum levels of obesity-related metabolic signaling molecules, including insulin, adiponectin, lipopolysaccharide (LPS) and the cytokines interleukin (IL)-1β and tumor necrosis factor (TNF)-α, were markedly improved." (PMID 32244807, 2020). "Adipose tissue secrets IL-1β that can trigger the neuroinflammatory response in obesity- and diabetes, it also secrets endocrine hormones such as leptin and adiponectin to mediate pro-cognitive effects of physical exercise." (PMID 33379163, 2020). "The results suggested that the underlying obesity following Western diet feeding worsened the GWI intestinal inflammation, as shown by increased levels of IL1β and IL6." (PMID 32927823, 2020). "Obesity and inflammation expand and mobilize MDSCs and their precursors via molecules such as IL-6, CRP, IL-1β, and leptin, increasing their susceptibility to tumor-derived signals that further drive their recruitment and suppressive capacity." (PMID 33123173, 2020). "IDO-deficient mice displayed elevated liver fibrosis, increased hepatic macrophage infiltration, and higher concentrations of IL-1β, IL-6, and IFNγ in obesity." (PMID 31921154, 2019). "P2X7 purinergic receptors (P2X7R), ligand gated ion-channels, are the key regulator of interleukin-1β (IL-1β) cleavage, which are important contributors to control the progression of obesity." (PMID 31681001, 2019). "Excessive IL-1β production is a characteristic of most chronic inflammatory diseases, including atherosclerosis, type 2 diabetes, and obesity, which affect a large proportion of the global population." (PMID 30894604, 2019). "Diet induced obesity increases airway hyperresponsiveness and the effects of obesity are preventable by caloric restriction and IL-1β blockade." (PMID 30670753, 2019). "MAP3K8 (also referred to as TPL2) was previously shown to be overexpressed in subcutaneous adipose (SQ) tissue from patients with obesity and this correlated with elevated levels of the inflammatory proteins IL-1β, IL-6, and IL-8." (PMID 31798691, 2019). "After 8 weeks of HFD and development of severe obesity, IL-1β mRNA levels remained elevated, but the IL-1β protein levels and secretion by pulmonary macrophages were no longer increased." (PMID 30670753, 2019).
Obesity (continued). "We conclude that obesity leads to the airway hyperresponsiveness preventable by caloric restriction and IL-1β blockade." (PMID 30670753, 2019). "Adipocyte hypertrophy is a classical manifestation of obesity and is directly associated with the aetiology of macrophage infiltration, hypoxia, secretion of pro-inflammatory cytokines (e.g., TNF-α, IL-6, IL-1β) and reduced production of adiponectin." (PMID 31133986, 2019). "Gevokizumab is an anti-IL-1β monoclonal antibody, IgG2, which improved glucose control and β-cell function in a diet-induced-obesity mouse model and in the presence of IL-1β-driven inflammatory diseases." (PMID 31182982, 2019). "IL-1β is a key cytokine that regulates the pathogenesis of many inflammatory diseases, for example, it is closely related to obesity-induced inflammation." (PMID 31681001, 2019). "It was proven that Dec1KO mice suppressed inflammation in periodontitis and obesity by decreasing inflammatory factors such as TNFα, IL-1β, and peroxisome proliferative active receptor gamma (PPARγ)." (PMID 31597354, 2019). "Obesity is associated with the recruitment of M1-polarized macrophages, which secrete pro-inflammatory cytokines such as TNF-α and IL-1β." (PMID 32063863, 2019). "In vitro treatment of KCs with FFAs (e.g., palmitate) promotes activation and secretion of inflammatory cytokines (e.g., IL-6, TNF, IL-1β) while KC depletion in vivo protects from obesity-driven hepatic steatosis." (PMID 31921154, 2019). "The recruited ATMs secrete both anti-inflammatory (interleukin-10 (IL-10) and IL-1) and pro-inflammatory (tumor necrosis factor-α (TNF-α), IL-6, and IL-1β) cytokines, suggesting they can serve both a protective and harmful role in obesity." (PMID 32133436, 2019). "The decline in NLRP3 inflammasome-mediated IL-1β activation also improves obesity-induced insulin resistance." (PMID 31174550, 2019). "IL-1β is a strong mediator of the obesity-induced inflammation and participates in the pathogenesis of T2D, mediating the adverse consequences of hyperglycemia on pancreatic β-cells." (PMID 32063863, 2019). "In the mouse model, IL-17, IL-1β and the NLRP3 inflammasome have been implicated in the pathogenesis of obesity-induced airway hyperresponsiveness." (PMID 30670753, 2019). "Together, this suggests that, while S100A8/A9 plays an important role in inducing IL-1β production, additional inflammatory signals within the adipose tissue likely co-signal to promote IL-1β and myelopoiesis in obesity." (PMID 31249530, 2019). "Activation of pyroptosis in obesity and metabolic syndrome is well-established as the release of IL-1β accelerates pancreatic β cell death." (PMID 31835893, 2019). "Our data in a non-allergy prone strain of mice showed that HFD activates the IL-1β pathway specifically in the lungs, prior to the development of significant obesity." (PMID 29686414, 2018). "Obesity induces ectopic lipid storage and inflammatory response, accompanied by the secretion of proinflammatory cytokines such as TNFα, IL1β and IL631." (PMID 29961765, 2018). "Percent body fat, plasma inflammatory markers associated with obesity (interferon (IFN)-γ, interleukin (IL)-10, IL-12 p70, IL-1β, IL-6 and KC/GRO), plasma Cur metabolites and liver telomere length were measured." (PMID 29445415, 2018). "This was parallel to the normalization in the expression of the macrophage markers F480 and CD68 and of the pro‐inflammatory cytokines TNF‐α and IL‐1β, indicating that FGF21 expression counteracted the inflammation of WAT associated with obesity." (PMID 29987000, 2018). "Another novel finding of the study is that HFD feeding induces IL-1β expression in lung tissue and increases IL-1β secretion in the lungs prior to the development of significant obesity." (PMID 29686414, 2018).